MRPL24 (mitochondrial ribosomal protein L24)
Synonyms: L24mt; MRP-L24; MRP-L18; uL24m
Tractability: Small molecule: a structure with a bound ligand is known. PROTAC: ubiquitination databases record sites on it; its protein half-life has been measured.
Gene: Protein-coding gene on chromosome 1 (156,737,294 to 156,741,590, reverse strand). Ensembl gene ENSG00000143314.
Subcellular location: Mitochondrion
Pathways (Reactome):
Metabolism of proteins: Mitochondrial ribosome-associated quality control; Mitochondrial translation elongation; Mitochondrial translation initiation; Mitochondrial translation termination
Gene Ontology:
Molecular function: structural constituent of ribosome; RNA binding
Biological process: mitochondrial translation; translation
Cellular component: mitochondrial large ribosomal subunit; mitochondrion; mitochondrial inner membrane; ribosome
Genetic constraint (gnomAD): Loss-of-function variants: 15 observed, 28.4 expected, observed/expected ratio (o/e) 0.53, 90% interval 0.35 to 0.81. The upper end of that interval is the gene's LOEUF score, 0.81, which puts it in group 3 of 6, group 1 being the genes least tolerant of losing a copy. Missense variants: 241 observed, 295.52 expected, observed/expected ratio (o/e) 0.82, 90% interval 0.73 to 0.91. Synonymous variants: 92 observed, 106.95 expected, observed/expected ratio (o/e) 0.86, 90% interval 0.73 to 1.02.
Gene-disease validity (ClinGen):
ClinGen rates the evidence that MRPL24 causes each of these diseases.
mitochondrial disease (autosomal recessive): Limited.
Homologues: Orthologues: chimpanzee MRPL24 (100% identical), macaque MRPL24 (95% identical), rabbit MRPL24 (92% identical), guinea pig MRPL24 (92% identical), pig MRPL24 (89% identical), rat mrpl24 (88% identical), mouse Mrpl24 (88% identical), tropical clawed frog mrpl24 (69% identical), zebrafish mrpl24 (65% identical), Drosophila melanogaster mRpL24 (50% identical), Caenorhabditis elegans mrpl-24 (37% identical).
Diseases named in the same sentence as MRPL24 in open-access papers:
MRPL24 is named in the same sentence as 10 diseases in open-access papers, as found by Europe PMC text mining. Sharing a sentence is not in itself a finding about the gene and the disease. The quoted sentences say what the papers report.
Cerebellar atrophy (1 paper, 2024). Cerebellar atrophy is defined as a cerebellum with initially normal structures, in a posterior fossa with normal size, which displays enlarged fissures (interfolial spaces) in comparison to the foliae secondary to loss of tissue. "Mutations in MRPL24 genes may result in cerebellar atrophy and intellectual disability." (PMID 38129360, 2024).
COVID-19 (1 paper, 2022). A disease caused by infection with severe acute respiratory syndrome coronavirus 2. "Among the transcripts related to the term “mitochondrial gene expression,” polyribonucleotide nucleotidyltransferase 1(PNPT1) showed the highest upregulation in the COVID-19 cohort, followed by MRPL24 and MRPS12." (PMID 36443881, 2022).
prostatitis (1 paper, 2025). An infectious or non-infectious inflammatory process affecting the prostate gland. "We revealed two Tier 2 genes (NOA1 and ELAC2) and one Tier 3 gene (ACAT1) for BPH, two Tier 3 genes (TRMU and SFXN5) for prostatitis, and six Tier 3 genes (MRPL24, NDUFS6, PUS1, NBR1, GLOD4, and PCBD2) for PCa." (PMID 40919435, 2025). "Our analysis revealed two Tier 2 genes (NOA1 and ELAC2) for BPH, two Tier 3 genes (TRMU and SFXN5) for prostatitis, and six Tier 3 genes (MRPL24, NDUFS6, PUS1, NBR1, GLOD4, and PCBD2) for PCa." (PMID 40919435, 2025).
tumor (2 papers, 2022 to 2025). "MRPL24, crucial for mitochondrial translation, could influence cellular metabolism and energy production, potentially affecting tumor growth and survival." (PMID 40919435, 2025).
mitochondrial disease (1 paper, 2022). "Mitochondrial disease-causing mutations were found in thirteen small ribosomal subunit mitoribosomal proteins (MRPS1, MRPS2, MRPS6, MRPS7, MRPS9, MRPS11, MRPS14, MRPS16; MRPS22, MRPS23, MRPS25, MRPS34, MRPS39) and four large ribosomal mitochondrial proteins (MRPL3, MRPL12, MRPL24, MRPL44)." (PMID 36140315, 2022).
MRPL24 also shares sentences with these, for which no sentence is quoted: Alzheimer disease (1 paper); cancer (1); Intellectual disability (1); lung carcinoma (1); Parkinson disease (1).